IL9 (interleukin 9)
Diseases named in the same sentence as IL9 in open-access papers (continued):
Sharing a sentence is not in itself a finding about the gene and the disease.
colitis (continued). "Given that claudin-1 and claudin-2 play distinct roles in epithelial barrier integrity, the differential regulation of these proteins by IL-9 across various colitis models may underlie the context-dependent role of IL-9/Th9 cells in colitis development." (PMID 40771819, 2025). "Moreover, IL-9-deficient mice in the TNBS-induced colitis model showed much less prominent goblet cell impairment, wound stimulation, and mononuclear cell deposition." (PMID 36769019, 2023). "The effect was associated with the increase in expression of claudin-2 expression with IL-9 treatment and reduction in claudin-2 expression with IL-9-deficiency, indicating that IL-9 disrupts intestinal permeability by enhancing the expression of claudin-2, which helps in promotion of colitis." (PMID 31035677, 2019). "Indeed, IL-9 is significantly reduced in oxazolone-induced colitis when GATA3 is deficient in T cells." (PMID 29910812, 2018). "Interestingly, in oxazolone colitis model, there was a downregulation in the expression of claudin 2 in IL-9-deficient mice than wild-type mice." (PMID 29881387, 2018). "In a TNBS-induced colitis model, IL-9-deficient mice were also resistant to colitis development and suggested that IL-9 may have a role in regulating intestinal barrier function." (PMID 29910812, 2018). "In chemically induced model of colitis, Th9 cells were found to be one of the major effector T cells population that induced disease pathogenesis, as both PU.1- and IL-9-deficient mice were found to have reduced incidence of colitis and reduced inflammatory score as compared to wild-type mice." (PMID 29867972, 2018). "Moreover, deficiency of PU.1+ IL-9+ T cells resulted in suppression of experimental colitis upon oxazolone treatment indicating a critical role of PU.1+ T cells in promoting UC in mice." (PMID 29881387, 2018). "Notably, IL-9 deficiency or neutralization protects mice from experimental colitis." (PMID 41030439, 2025). "In addition, PU.1-dependent IL-9 induction was linked to the pathology of intestinal inflammation, as IL-9 deficient as well as Spi conditional deficiency in T cells were seen to have reduced clinical and histological signs in oxazolone-induced colitis model." (PMID 29867972, 2018). "Importantly, treatment with an IL-9 antibody or IL-9 knockout in mice considerably reduces colitis, as indicated by weight loss, generation of reactive oxygen species, and clinical scores, indicating that IL-9 promotes the progression of colitis." (PMID 27589682, 2016). "Conversely, treatment of colitis mice with an anti-IL-9 antibody resulted in the reduced expression of IL-6, TNF-α, IL-1β, IL-10, and IL-22 in colonic tissues and decreased percentage of PU.1+ Th9 cells in the lamina propria and improved the clinical outcomes." (PMID 40771819, 2025). "Modulating the Treg/Th2 response by decreasing proinflammatory cytokines such as TNFα, IL-6, IL-1β, IL-18, IL-22, IL-9 and increasing anti-inflammatory cytokines IL-10 and IL-4 in mice colitis model." (PMID 41208998, 2025). "IL-9-/- mice treated with TNBS exhibited attenuated colitis compared to control mice treated with TNBS alone." (PMID 40771819, 2025). "With respect to the role of IL-9 and Th9 cells in colitis pathogenesis, adoptive transfer of Th9 cells into colitis mice induced weight loss, shortened colon length, increased leukocyte infiltration, and damaged glandular architecture." (PMID 40771819, 2025). "The frequency of Th9 cells is increased in mice with various forms of IBD-like colitis (i.e., DSS- and TNBS-colitis and T cell transfer colitis), and neutralization of IL-9 in such models attenuates the ongoing inflammation." (PMID 41194916, 2025). "In the Th2-dominant oxazolone-induced colitis mouse model, IL-9 expression is increased throughout the intestinal tract, and the number of intestinal and splenic IL-9+ CD4+ T-cells is higher than in control mice." (PMID 36769019, 2023).
colitis (continued). "EpCAM expression appeared to be as severe as in the AOM/DSS colitis mice, for example, in line with heightened IL-9 levels." (PMID 37275854, 2023). "A population of T helper cells co-expressing IL-9 and IL-4 was already reported in the literature, indicating that this population can activate eosinophils in colitis and is involved in the effector function of T helper cells in this disease." (PMID 37676302, 2023). "Experimental models of colitis have underscored the critical interference of IL-9-producing T cells with an intact intestinal barrier function, influencing cellular proliferation and tight junction molecules." (PMID 38137450, 2023). "Functional studies in the murine DSS and AOM/DSS models identified an important role of IL-9 and Th9 cells in driving colitis activity and tumour growth in vivo." (PMID 35793807, 2022). "Induction of IL-9 is correlated with the severity of gut pathology, and blockage of IL-9 with neutral antibody suppresses the progression of colitis in mice." (PMID 33777009, 2021). "Yeti iNKT cells displayed a pronounced anti-inflammatory (IL4- or IL9-producing) phenotype during colitis." (PMID 33513946, 2021). "SSP and 5-ASA significantly reduced IL-1β, IL-4, IL-9, and IL-17A concentrations in the colitis mice, followed by lower expression of the CD11c+CD103+E-cadherin+ and CD11c+CD103+TNF-α+ cells." (PMID 32754049, 2020). "In a mouse model of colitis induced by the hapten oxazolone, expression of Il9 is upregulated similar to UC." (PMID 31035677, 2019). "We were able to show that blocking IL-9 signaling by intraperitoneal administration of IL-9 antibody rapidly ameliorates colorectal inflammation in DSS-induced colitis mice." (PMID 31637216, 2019). "In one study, the injection of anti-IL-9 antibody for two weeks reduced the severity of inflammation in DSS-induced colitis mice, suggesting the role of IL-9 in pathogenesis of UC." (PMID 31035677, 2019). "In our model, IL-9 increased during colitis and its levels were back to normal after feeding with P100K EVs." (PMID 31601878, 2019). "It has been observed that neutralization of IL-9 inhibits intestinal inflammation in oxazolone-induced colitis model." (PMID 29881387, 2018). "Consistently, treatment with anti-IL-9 neutralizing antibody was found to effectively control tissue inflammation of intestine in colitis." (PMID 29867972, 2018). "Nonetheless, the protective role of IL-9 was also attributed in DSS-induced colitis, as NKT cells-driven IL-9 is found to protect gut inflammation in DSS-induced colitis." (PMID 29867972, 2018). "The potential mechanism for Th9-mediated colitis has been unraveled by investigating the function of Th9 cells and IL-9 in regulating the expression of tight junction proteins essential for maintaining intestinal barrier integrity." (PMID 29881387, 2018). "IL-9 induced inflammation in mucosal epithelial cells and promoted colitis upon treatment with TNBS." (PMID 29881387, 2018). "This suggests that the potential mechanism for IL-9-mediated colitis involves disruption of the intestinal barrier culminating in increased bacterial entry into the mucosa and associated pro-inflammatory responses." (PMID 29881387, 2018). "In oxazolone-mediated colitis model also there was an increase in the expression of IL-9 and IL-9R by intestinal epithelial cells." (PMID 29881387, 2018). "IL-9-producing type I NKT cells protect against DSS-induced colitis through IFN-γ and IL-17A suppression, as well as IL-10 and TGF-β upregulation, depending on IL-4 production by type I NKT cells." (PMID 28095507, 2017). "In acute and chronic IBD mouse models, numbers of IL-9-producing cells and IL-9R levels increased during colitis." (PMID 27589682, 2016). "The discovery that IL-9 deficiency reduced colitis activity in the TNBS (T-cell-mediated colitis induced by the hapten reagent 2,4,6-trinitrobenzenesulfonic acid)-induced colitis model emphasizes the broad relevance of IL-9 in T-cell-dependent intestinal inflammation." (PMID 38137450, 2023).
colitis (continued). "The role of TH9 cells in CRC is not clear as IL-9 has a strong inflammatory activity in experimental colitis, leading to colitis-associated cancer." (PMID 36611932, 2022). "Anti-IL-9 antibodies also restrained colitis, suggesting that IL-9 could be used efficiently for colitis therapy." (PMID 35793807, 2022). "Furthermore, we analysed colitis-associated tumours and detected even higher levels of Th9-associated factors and marked correlations between GATA3, SPI.1, and IL-9 mRNA levels, suggesting the relevance of Th9 cells in these patients." (PMID 35793807, 2022). "Similarly to IL-9 inactivation, deficiency of PU.1 in T cells suppressed DSS colitis after the third cycle of DSS treatment." (PMID 35793807, 2022). "Colitis can activate Th1 cells, resulting in the release of Th1-related cytokines such as IFN-γ, while ulcerative colitis is associated with Th2 and the release of IL-5, IL-13, and IL-9." (PMID 35240996, 2022). "The pathological role of IL-9 has mostly been demonstrated in several murine colitis models." (PMID 31906479, 2020). "Administration of IL-9 blocking antibody improved oxazolone-induced murine colitis." (PMID 31886308, 2019). "Moreover, abundant IL-9R expressing intestinal epithelial cells were observed in the gut mucosa of UC patients indicating the role of IL-9 and Th9 cells in promoting colitis." (PMID 29881387, 2018). "Moreover, IL-9 secreted by iNKT cells in the DSS-mediated colitis model also dampened the immune response by inducing the release of IL-10 and TGF-β (anti-inflammatory cytokines)." (PMID 29881387, 2018). "However, similar reports on IL-9, particularly Th9 cells in human autoimmune conditions are limited, except a few notable very recent studies in psoriasis, colitis, and RA." (PMID 29382374, 2018). "Interestingly, work using an experimental chronic colitis model induced by DSS has shown that VEGF‐C can reduce intestinal inflammation by regulating IL‐9/IL‐17 balance and improving the gut microbiota." (PMID 30324649, 2018). "Moreover, IL-9 deficiency resulted in reduced number of PU.1+ T cells and protected mice from colitis in TNBS-colitis model indicating a role of Th9 cells and their secretory cytokine in the regulation of mucosal inflammation-mediated colitis." (PMID 29881387, 2018). "This indicates that IL-9 might disrupt intestinal permeability by enhancing the expression of claudin 2 in oxazolone-mediated colitis." (PMID 29881387, 2018). "Likewise, in colitis and myasthenia gravis IL-9 has been demonstrated to potentiate the inflammatory pathologies." (PMID 29382374, 2018). "In contrast, silencing TAF1 expression in IL-9-stimulated fibroblasts reduced the expression of Col1a1, Col3a1, collagen I, and collagen III, suggesting that IL-9 interacts with ETV5 and subsequently regulates TAF1, thereby contributing to the production of colitis-associated inflammatory factors." (PMID 40771819, 2025). "Interestingly, in the TNBS-induced colitis mouse model, which features a potent Th1 response that resembles CD, mice lacking IL-9 show less severe inflammation and weight loss than wild-type mice." (PMID 36769019, 2023). "Therefore, some of the beneficial effects of P100K milk EVs on colitis might come from the reduction of the IL-9/miR-21/CLDN8 pathway, which would impact RhoB, reduce gut permeability and modulate the microbiota." (PMID 31601878, 2019). "Thus, it could be suggested that IL-9 promotes colitis by regulating the expression of different tight junction molecules in different inflammatory conditions." (PMID 29881387, 2018). "In contrast, we noted here that IL-9 deficiency had a mild anti-inflammatory effect in chronic DSS colitis only after the third DSS cycle, suggesting that IL-9 has a limited pro-inflammatory capacity in the AOM/DSS model under our experimental conditions." (PMID 35793807, 2022). "Both experimental murine colitis models and patient studies argue for a role of CD4+ T-cell derived IL-9 in IBD." (PMID 31906479, 2020).
colitis (continued). "Those that were upregulated by 1 log fold or higher include IL-9, IL-13, IL-4, IL-17A, IL-5, IL-24, IFN-γ, IL-10, IL-11, and IL-27, many of which are known cytokines involved in the pathogenesis of colitis." (PMID 21365015, 2011). "A lack of IL-9 in the oxazolone-induced colitis model was found to reduce histological and disease symptoms and to enhance intestinal-barrier function." (PMID 36769019, 2023). "iNKT cells (particularly IL-9-producing iNKT cells) also up-regulate IL-22-producing ILC3s in the mLNs, ultimately preventing DSS-induced colitis under IFN-γ-dysregulated conditions, indicating that iNKT cells and ILC3s counter-regulate IFN-γ-mediated intestinal inflammation." (PMID 38274786, 2023). "Mice lacking PU.1 in T cells were shielded from colitis, and the administration of an IL-9 antibody suppressed colitis." (PMID 38137450, 2023). "The elevated levels of IL-1α, IL-1β, IL-3, IL-6, IL-9, IL-12 (P40), IL-12 (P70), IL-17, GM-CSF, and G-CSF in response to DSS treatment in the current study, supports the strong involvement of macrophage activation in the DSS induced colitis model." (PMID 36365201, 2022). "In accordance, we found that, after induction of colitis by DNBS, the signaling cascade through transcription factor NF-κB activation was markedly increased, as well as the level of pro-inflammatory cytokines such as IL-5, IL-9, and IL-13." (PMID 35893393, 2022). "TL1A may promote the differentiation of Th9 cells and enhance IL-9 secretion by upregulating the expression of TGF-β, IL-4, and PU.1, thus exacerbating DSS-induced murine colitis." (PMID 31886308, 2019). "In the amygdala, the mutant A allele led to lower levels of IL-1α, IL-9, macrophage inflammatory protein (MIP)-1β, and MIP-2 independent of colitis—providing additional understanding of how FAAH may serve as a regulator of inflammatory responses in the brain." (PMID 34916909, 2021). "Absence of IL-9 protects mice from trinitrobenzene sulfonic acid (TNBS)- induced colitis." (PMID 31906479, 2020). "Since it has been demonstrated that IL9-producing iNKT cells provide protective effects against DSS colitis in an IL4-dependent manner, we decided to examine whether this subset of iNKT cells cooperates with IL22-producing ILC3s in regulating colitis in Yeti mice." (PMID 33513946, 2021). "Transcriptional studies have revealed that the production of IL-9 by TH9 cells is regulated by PU.1 (an ETS family transcription factor), and there is ample evidence to suggest that the TH9 cytokine IL-9 could be a strong proinflammatory factor in the induction of experimental colitis." (PMID 31637216, 2019). "However, the role of STAT6 and SMADs on IL-9 production in colitis has not been examined." (PMID 29910812, 2018). "However, it is not known whether blockade of IL-9 in other mice models of colitis would also give similar results or not." (PMID 29881387, 2018). "In a novel IL-9 reporter mouse, CD4+T cells, but not other cell types such as innate lymphoid cells, are the principal source of IL-9 in colitis." (PMID 27589682, 2016).
helminth infections (37 papers, 2008 to 2026). "ILC2s have been implicated in immune responses to extracellular helminth infections via the secretion of the type 2 cytokines IL-4, IL-5, IL-9 and IL-13." (PMID 40591723, 2025). "The immunological hallmark of helminth infections is their ability to induce Th-2 associated immune responses characterized by the presence of the IL-4, IL-5, IL-9, IL-10, and IL-13." (PMID 35087402, 2021). "The previous research of defense mechanisms against helminths infections is typically associated with a type 2 immune response characterized by the expression of the cytokines IL-3, IL-4, IL-5, IL-9, IL- 10, and IL-13." (PMID 32243446, 2020). "As a prototypical type 2 cytokine, IL-9 has been implicated in many diseases, especially helminth infections." (PMID 28539607, 2017). "IL-9 was a prototypical type 2 cytokine, which has been implicated in many diseases, especially helminth infections." (PMID 28539607, 2017). "This may even extend to mediators such as IL-9, which is not only upregulated in helminth infection, but more intensely so in IL-6-deficient mice." (PMID 24185641, 2014). "Accumulating evidence suggest that IL-9 is of particular relevance in controlling intestinal helminth infections." (PMID 41901710, 2026). "ILC2-derived IL-9 induces airway eosinophilic inflammation by activating ILC2s themselves in an autocrine manner during helminth infection, indicating that IL-9 is also crucial for ILC2 function and survival." (PMID 37371472, 2023). "On the other hand, IL-9 has beneficial effects in initiating immunity against helminth infection and tumors." (PMID 37893164, 2023). "In this work we report the presence of distinct ILC2 populations based on ST2 and IL-9 expression in a helminth infection model." (PMID 35711429, 2022). "Within these type 2 cytokines, IL-9 plays an essential role in the immune system defense against helminth infections." (PMID 35711429, 2022). "The physiological function of IL-9 seems to be in some way connected with a Th2 response, as IL-9 is important in the immune defense against helminth infection but also appears during allergic reactions in the lung, both scenarios that depend on Th2 responses." (PMID 31936604, 2020). "In another study, IL-9 produced by non-Th2 CD4+ T cell subset during early Nippostrongylus brasiliensis infection in mice provided sufficient host protection against worm infection." (PMID 32243446, 2020). "The genetic background of the host was also relevant for the regulation of IL-9 production during intestinal helminth infection." (PMID 29872093, 2018). "Helminth infections are usually associated with Th2-type immune response characterized by the activation of CD4+ T helper cells and secretion of IL-4, IL-5, IL-9 and IL-13." (PMID 30189894, 2018). "During helminth infections, there is a predominant Th2 response characterized by a high production of IL-4, IL-5, IL-9, IL-10 and IL-13 cytokines." (PMID 27783986, 2016). "The role of IL-9 in helminth infection was first suggested by animal studies showing that IL-9 transgenic mice infected with Trichuris muris or Trichinella spiralis had an increased Th2 response and faster expulsion of the parasite from the intestine." (PMID 26730582, 2016). "This study also confirms data from the animal models of helminth infection showing expansion of IL-9 expressing CD4+ T cells." (PMID 26730582, 2016). "It has been demonstrated that helminth infections strongly induce an immune response involving elevated Th2 cytokines (i.e., IL-4, IL-5, IL-9, and IL-13), IgE, IgA, eosinophilia, and mucus secretion." (PMID 27882241, 2016). "IL-9’s role in helminth infection has recently been suggested in two consecutive studies showing that IL-9 transgenic mice infected with either T. muris or T. spiralis had an increased Th2 response and faster expulsion of the parasite from the intestine." (PMID 25360134, 2014).